MYCN (MYCN proto-oncogene, bHLH transcription factor)
Diseases named in the same sentence as MYCN in open-access papers (continued):
Sharing a sentence is not in itself a finding about the gene and the disease.
neuroblastoma (continued). "We found that METTL1 highly expressed in high risk NBL based on the Children’s Oncology Group (COG), advanced NBL according to the International Neuroblastoma Staging System (INSS), and NBL with MYCN amplification." (PMID 36071474, 2022). "We proposed a candidate treatment that is expected to be particularly effective for neuroblastomas with enhanced PHGDH expression, i.e., with MYCN amplifications and 11q LOH and poor prognosis." (PMID 36319669, 2022). "Downregulation of MYC or MYCN protein expression upon MYCMI-7 treatment was also confirmed in HeLa, P493-6, HCT116 cells, and in MYCN-amplified Kelly neuroblastoma cells." (PMID 36874405, 2022). "By targeting MYCN and AKT2, miR-184 had a positive effect on inhibiting neuroblastoma cell survival." (PMID 35846139, 2022). "Here, we first time show that in neuroblastoma cells iron chelator VLX600 inhibits mitochondrial respiration, decreases expression levels of MYCN/LMO1 (LIM domain only 1), and induces an efficient cell death regardless of MYCN status." (PMID 35805002, 2022). "Targeting this part of the pathway in conjunction with canonical inhibitors like BSO may be an exciting avenue of therapy for MYCN-amplified NB, and advances our understanding of how MYCN meets the enhanced GSH reliance in MYCN-amplified neuroblastoma." (PMID 35174317, 2022). "In vitro experiments in neuroblastoma cells have shown that up-regulation of miR-15a-5p, miR-15b-5p or miR-16-5p can reduce expression of MYCN transcript and N-Myc protein." (PMID 35586497, 2022). "Relationships between the four-gene signature and the clinical characteristics of neuroblastoma, including the INSS (International Neuroblastoma Staging System) stage, age, MYCN status, and tumor progression, were analyzed in both datasets." (PMID 35664308, 2022). "Cross-validation using the entire cohort and the public domain expression data verified the overall lower expression of these genes not only in retinoblastomas with a MYCN-amplified RB1-proficient background, but also in MYCN-amplified neuroblastomas." (PMID 36245757, 2022). "MYCN amplification and MYC expression have been shown to correlate with a neuroblastoma tumor microenvironment low in infiltrating immune cells and low cellular immunity, suggesting its role in suppressing immunogenicity." (PMID 35326601, 2022). "Recent data from genetically engineered mouse models of neuroblastoma confirm that ALK and MYCN cooperate to promote tumorigenesis." (PMID 34716856, 2022). "Surprisingly, ASCL1 deletion had little effect on the transcription of CRC gene transcripts in these neuroblastoma cell lines, but the ability of MYC/MYCN and CRC component proteins, PHOX2B and GATA3, to bind to chromatin was compromised." (PMID 36263020, 2022). "In neuroblastoma, HMGA1 is regulated by MYCN in the MYC protein family, and abnormal expression of MYCN affects overexpression of HMGA1." (PMID 35629376, 2022). "In contrast, SESN1 expression was downregulated in paediatric neuroblastoma patients with MYCN amplification in the TARGET, E-MTAB-161, E-MTAB-1781, E-MTAB-8248, E-TABM-38, GSE16476, GSE49710 and GSE85047 independent paediatric neuroblastoma cohorts." (PMID 35655142, 2022). "Further analysis of miR-186 revealed targets including MYCN, AURKA and several TGFB-pathway members like TGFBR1, TGFBR2, SMAD2 and SMAD3 important for survival and immune escape mechanisms in neuroblastoma." (PMID 36793342, 2022). "We determined the mRNA copy levels of MYC and MYCN in SU-DIPGVI and HSJD-DIPG007 and found low copy numbers of both genes in comparison to known amplified neuroblastoma cultures (SJ-G2 and BE2C)." (PMID 33579942, 2021). "Concomitant amplification or copy number gain of two genes is a common phenomenon in cancers, such as MYCN and DDX1 in neuroblastoma, ERBB2/HER2 and TOPOIIα in prostate cancer." (PMID 34461927, 2021).
neuroblastoma (continued). "Subsequent studies have also verified the tumor suppressive impact of miR-34a in the neuroblastoma cells and its inhibitory effects on the expression of BCL2 and MYCN." (PMID 33718173, 2021). "We showed that TOP2B remains overexpressed in neuroblastoma, particularly in younger and neonatal patients and that TOP2B expression is driven higher by MYCN overexpression, explaining the selective activity of CX-5461 against neuroblastoma cells." (PMID 34753908, 2021). "The product of the MYCN amplicon is a transcription factor belonging to the MYC family of oncoproteins, frequently activated in neuroblastoma and other childhood malignancies." (PMID 34847775, 2021). "We have recently shown that PARPs are overexpressed in MNA neuroblastoma, and that PARP inhibitors with high trapping properties enhance MYCN-dependent RS and activate S and G2/M checkpoints." (PMID 34508175, 2021). "The prognosis is significantly correlated with multiple factors, including the age of diagnosis, site of onset, International Neuroblastoma Staging System (INSS) stage, MYCN amplification status, and DNA ploidy." (PMID 34746127, 2021). "Taken together, our data show that DDX21 induces CEP55 expression, MYCN‐amplified neuroblastoma cell proliferation, and tumorigenesis, and that DDX21 and CEP55 are valid therapeutic targets for the treatment of MYCN‐amplified neuroblastoma." (PMID 33497018, 2021). "Similar findings were observed in neuroblastoma driven by the expression of the ALK and MYCN genes with lorlatinib and crizotinib, respectively." (PMID 34063424, 2021). "At this study’s initiation, recognized risk driving factors included stage defined by the International Neuroblastoma Staging System (INSS), age at diagnosis, and MYCN oncogene amplification (MNA) status." (PMID 33540616, 2021). "Pediatric neuroblastoma patients in TARGET, GSE49710 and GSE85047 datasets were divided into four sub-groups based on the mean age and MYCN amplification status." (PMID 34116676, 2021). "Combination drug treatment with SAHA and SE486-11 reduced MYCN, USP5 and PCNA (proliferation marker) protein levels in neuroblastoma-bearing MYCN;GFP zebrafish compared to DMSO treated controls." (PMID 33658627, 2021). "MYCN bound to the USP5 promoter and induced USP5 gene expression suggesting that USP5 and MYCN expression created a forward positive feedback loop in neuroblastoma cells." (PMID 33658627, 2021). "What happens in neuroblastoma when the troika of ALKAL2, ALK, and MYCN are aberrantly expressed, or activated, in either 2p-gain or amplification?" (PMID 34885007, 2021). "The relationship between MYCN expression and EV protein cargo was investigated using the TET21-N neuroblastoma cell line." (PMID 34847775, 2021). "This likely is of pivotal importance in MNA neuroblastoma, where IGF2BP1 probably serves as a MYCN-driven antagonist of MYCN-inhibitory miRNAs upregulated in MNA neuroblastoma." (PMID 34026620, 2021). "It will be interesting to study the function of Lamin A/C to further disentangle MYCN and NTRK1-regulated circuits, which are at the crossroads between proliferation and differentiation in neuroblastoma cells." (PMID 34771457, 2021). "Thereby, neuroblastoma cells with high Aurora A expression are less dependent on growth factor and active PI3K/AKT signaling to maintain high MycN levels 61,62." (PMID 33390782, 2021). "Subsequently, two MYC paralogues, MYCN (initially identified in neuroblastomas) and MYCL, were cloned in neuroblastoma and lung cancers, respectively." (PMID 34201047, 2021). "Sensitivity to BET inhibition is correlated to amplification and/or overexpression of the respective driver genes in both medulloblastoma and neuroblastoma, i.e., MYC and MYCN, respectively." (PMID 33668642, 2021).
neuroblastoma (continued). "For this purpose, we used four neuroblastoma cell lines with inducible NTRK1 expression and activation, two of which were harboring MYCN amplification (IMR5, NGP), while the other two had normal MYCN copy numbers (SH-SY5Y, SKNAS)." (PMID 34771457, 2021). "Collectively, these data suggest that although high expression of both ACACA and FASN consistently correlates to reduced survival in tumors independently of their MYCN status, FASN seems to be a better prognosis marker candidate for neuroblastoma patients." (PMID 33659885, 2021). "MYCN and ALK copy number was assessed in cfDNA samples from 16 patients with active neuroblastoma (14 at initial presentation and 2 at metastatic recurrence) and 3 patients in remission." (PMID 34282791, 2021). "We have shown that USP5 and MYCN directly interact in untreated neuroblastoma cells and, that combination therapy lowered USP5 and MYCN protein levels." (PMID 33658627, 2021). "In a study comprising a large cohort of neuroblastoma cases registered with the Children’s Oncology Group study, 11q LOH and 1p LOH or MYCN amplification were independent poor prognostic markers as determined by multivariable analysis." (PMID 34796286, 2021). "In neuroblastoma, studies have reported that the MCM complex is directly regulated by the transcription factor MYCN, but there are very few studies on the tumor characteristics and prognosis of MCM6 and neuroblastoma." (PMID 34233647, 2021). "In neuroblastoma, AHCY expression is elevated in MYCN-amplified tumor samples and neuroblastoma cell lines." (PMID 33869213, 2021). "Using five small molecule inhibitors targeting ACACA or FASN and siRNA targeting FASN, we show that inhibition of fatty acid synthesis decreases cell proliferation, reduces MYCN or c-MYC protein levels, and results in neural differentiation in neuroblastoma." (PMID 33659885, 2021). "From the library’s lead compounds, we further evaluated CBP/p300 bromodomain inhibitors as potential MYCN amplified neuroblastoma therapeutics, since CBP (CREBBP) was prominent in our MYCN-related -omic and neuroblastoma patient outcome analysis." (PMID 33968920, 2021). "The EUH subset includes (i) MYC-driven neuroblastoma expressing high MYC and/or MYCN protein, (ii) Neuroblastoma with TERT overexpression due to genomic rearrangements, and (iii) Neuroblastoma of the ALT group due to ATRX loss." (PMID 33968044, 2021). "Consistent with an MYCN-ALYREF-USP3 signal driving neuroblastoma tumorigenesis, we found that high USP3 mRNA expression in the SEQC neuroblastoma patient cohort (n = 498) also correlated with poor prognosis." (PMID 33767157, 2021). "We further explored whether expression of these markers was dependent on the genetic subtype and evaluated our RNA-seq dataset for DTC marker expression in neuroblastoma with and without MYCN-amplification, loss of chromosome 11q or other neuroblastoma-specific genetic aberrations." (PMID 34503120, 2021). "On the contrary, IGF2BP1 upregulation in MNA neuroblastoma is supported by previous studies in primary tumors, MYC/MYCN-driven transcriptional regulation and conserved oncofetal expression of the protein." (PMID 34026620, 2021). "This is consistent with the reported role of ELAVL4 in antagonizing downregulation of MYCN expression by miR-17 and recently reported roles in the 3’UTR-dependent enhancement of mRNA translation in neural and neuroblastoma-derived cells." (PMID 34026620, 2021). "In addition, MYCN amplification status is a robust prognostic marker of outcome, but with the intensification of chemoradiotherapy, recent high-risk neuroblastoma trials showed no impact on outcome for patients whose tumors harbor MYCN amplification, unlike legacy high-risk trials in the past." (PMID 33918978, 2021).
neuroblastoma (continued). "We also observed that neuroblastoma cell lines showed marked dependency on USP3 for cell viability, especially in the MYCN-amplified context." (PMID 33767157, 2021). "In MYCN-amplified neuroblastoma, binding of Aurora-A to an overlapping region reduces FBXW7 binding to N-Myc." (PMID 33981003, 2021). "High ALYREF mRNA expression correlated with MYCN mRNA expression in the TARGET25 (n = 154), SEQC29–32 (n = 498), and Kocak34 (n = 476) neuroblastoma patient tumor data sets." (PMID 33767157, 2021). "The involvement of PTPs in the regulation of neuroblastoma cell signaling and development mediated by the distinct RTK/MYCN axes argues for PTPs as relevant biomarkers and potential therapeutic targets in this type of cancer." (PMID 34957126, 2021). "The five-gene signature had good performance in predicting survival and was demonstrated to be superior to International Neuroblastoma Staging System (INSS) staging and the MYCN amplification status." (PMID 34950701, 2021). "Our analysis showed that high levels of both ACACA and FASN correlate with reduced survival in three neuroblastoma patient cohorts covering all five INSS stages and with similar proportion of MYCN-amplification." (PMID 33659885, 2021). "Our results show that the A and G alleles of the ODC1 G316A promoter SNP differentially affect ODC1 expression, as well as MYCN-mediated ODC1 transactivation of the E-box region and MYCN oncogenic processes in neuroblastoma cells in vitro." (PMID 33918978, 2021). "Additionally, a systematic comparison of N-linked glycomic variations between different neuroblastoma cell lines revealed that less galactosylated and more sialylated N-glycan structures were found in MYCN-amplified cell lines compared with MYCN-nonamplified cell lines." (PMID 33796450, 2021). "The transgenic expression of MYCN in the neural crest lineage of mice or zebrafish alone, or in combination with LMO1 or activated ALK gives rise to neuroblastomas." (PMID 33628735, 2020). "In neuroblastoma cells, LIN28B promotes AURKA expression and increases MYCN expression by repressing let-7 miRNAs." (PMID 33194665, 2020). "We decided to further explore the connection between MYCN transcription factor and VRK1 in neuroblastoma." (PMID 33233777, 2020). "We went on to additionally define PBK as a direct transcriptional target of MYCN, thus linking PBK to two neuroblastoma oncogenes, LIN28B and MYCN." (PMID 32923517, 2020). "These included SKP2 or MYCN, confirming prior data, and ID2, which drives oncogenesis in other RB1null and RB1wt/MYCNamp contexts, including neuroblastoma." (PMID 32572160, 2020). "Further studies have shown that although TERT alterations and MYCN amplification do co-exist in a small proportion of cases, there is no overlap between the telomerase expressing and ALT positive neuroblastoma." (PMID 32375866, 2020). "In MYCN-amplified neuroblastoma cells, NGF suppressed MYCN gene expression through mitogen-activated protein kinase signaling pathways." (PMID 33937011, 2020). "Although both MYCN and MYC upregulation occurs in the childhood cancer neuroblastoma, elevated MYCN is the strongest predictor of a poor prognosis." (PMID 33092025, 2020). "Our results demonstrate that MycN and c-Myc tightly cooperate in regulation of the CSC phenotype and radioresistance properties in neuroblastoma cells upon glutamine deprivation." (PMID 32483461, 2020). "N-Myc activates GLDC transcription and is essential for maintaining high levels of GLDC expression in MYCN-amplified neuroblastoma cells, suggesting that GLDC and other SGOC pathway genes are cooperatively upregulated." (PMID 32547946, 2020).
neuroblastoma (continued). "This study investigates the influence expression of the MYCN oncogene has on the DNA damage response, replication fork progression and sensitivity to PARP inhibition in neuroblastoma." (PMID 32577161, 2020). "Interestingly, in neuroblastoma cells carrying MYCN extrachromosomal amplified copies, nuclear blebs and micronuclei containing MYCN copies were reported, raising the possibility that the interphase breakage model might not be restricted to cells with HSRs, but could also apply to cells with DMs." (PMID 33334014, 2020). "Our work suggests that VRK1 synergize with MYCN to drive NB progression and that VRK1 inhibition may constitute a novel cell-cycle-targeted strategy for anticancer therapy in neuroblastoma." (PMID 33233777, 2020). "As expected, copy number amplification of MYCN was detected in the KELLY and IMR-32 neuroblastoma models as were characteristic gene rearrangements in alveolar rhabdomyosarcoma (aRMS) (PAX3-FOXO1) and Ewing sarcoma (EWS-FLT1) models." (PMID 32076484, 2020). "Here, we demonstrate that in cultured neuroblastoma tumour cells, RAMBAs enhance RA action as seen by morphological differentiation, AKT signalling and suppression of MYCN protein." (PMID 31903789, 2020). "MYCN amplification (MNA) is the strongest indicator of poor prognosis in neuroblastoma (NB)." (PMID 32015512, 2020). "We recently reported that TRIM32 promoted the proteasomal degradation of MYCN at spindle poles during cell division, while TRIM32 overexpression induced ACD in human neuroblastoma cells." (PMID 33194665, 2020). "Past studies showed that MYCN upregulates MDM2 RNA in neuroblastoma cells by binding to MDM2 promoter E-box sequences, and we here corroborate that ectopic MYCN upregulates MDM2 in MYC-expressing SH-SY5Y." (PMID 33425720, 2020). "As our results suggested a compensatory mechanism involving MYCN and c-MYC in MYCN-amplified neuroblastoma cells upon glutamine deprivation, we also performed the 3D colony-forming assay following c-MYC knockdown." (PMID 32483461, 2020). "MYCN was early found to form extrachromosomal double minutes in neuroblastoma (NB)." (PMID 33585252, 2020). "Among 10 high-MYCN-expressing cell lines examined in this and other studies, including five retinoblastoma, three neuroblastoma, and two SCLC lines, all required high-level MDM2 expression for MYCN expression and viability." (PMID 33425720, 2020). "Together, we have validated both MYCN and MYC ChIP-Seq antibodies for use in ChIP-Seq, as well as genome-wide occupancy profiles for histone markers and open chromatin across a cohort of neuroblastoma cell lines." (PMID 32286315, 2020). "A logistic regression model was used for MYCN Proto-Oncogene, BHLH Transcription Factor (MYCN) gene amplification in neuroblastoma." (PMID 33166334, 2020). "Taken together, these findings provide evidence that PROTAC BET inhibitor is an efficient way to achieve MYCN/c-Myc manipulation, and ARV-825 can be used as a potential therapeutic strategy for the treatment of neuroblastoma." (PMID 33324552, 2020). "Two Aurora-A kinase activity inhibitors, MLN8054 and MLN8237, disrupt the Aurora-A/N-MYC complex and promote FBXW7-mediated degradation of N-MYC, which correlates with tumor regression and prolonged survival in a mouse model of MYCN-driven neuroblastoma." (PMID 33614505, 2020). "In particular, in neuroblastoma, ALK events cooperate with MYCN amplification to accelerate neuroblastoma development and progression." (PMID 32059449, 2020).